MTOR (mechanistic target of rapamycin kinase)
Diseases named in the same sentence as MTOR in open-access papers (continued):
Sharing a sentence is not in itself a finding about the gene and the disease.
tumor (continued). "The PI3K/AKT/mTOR has become an essential therapeutic target in several solid cancers because of its pivotal function in tumor proliferation, survival, and resistance to therapy." (PMID 40740483, 2025). "Tumor cells leverage mTOR signaling to promote proliferation, metabolic reprogramming, and resistance to therapy." (PMID 41301687, 2025). "The activation of the PI3K/Akt/mTOR pathway leads to increased drug resistance in tumor cells, inhibits tumor cell apoptosis, and promotes tumor cell survival." (PMID 40077417, 2025). "Everolimus (RAD-001), an mTOR inhibitor, has been shown to reduce tumor cell growth both in vitro and in vivo in xenograft models using NCI-H295R cells." (PMID 40145087, 2025). "This study identified the cellular senescence gene ETS2 as a tumor suppressor in THCA, which interacts with ZMYND11 to regulate THCA tumor progression through the mTOR pathway, thereby inhibiting cell senescence." (PMID 40938895, 2025). "The review highlights metformin as the most promising anti-diabetic agent for OC management, showing anti-tumor effects through mTOR inhibition." (PMID 41296433, 2025). "Recent evidence also establishes the comprehensive advantage of mTOR inhibitors in reducing non-tumor-related mortality." (PMID 41375072, 2025). "Targeted therapies, such as tyrosine kinase inhibitors (TKIs) and mammalian target of rapamycin (mTOR) inhibitors, have improved patient outcomes by targeting specific molecular pathways involved in tumor growth and angiogenesis." (PMID 39882192, 2025). "Mounting evidence suggests that phosphoinositide 3 kinase (PI3K)/Akt/mammalian target of rapamycin (mTOR) signaling pathway (PAM) is commonly altered in TNBC that drives tumor progression and therapy resistance." (PMID 40552278, 2025). "Both preclinical and clinical investigations demonstrate that rapamycin inhibits tumor growth by blocking mTOR-driven cell cycle progression and promoting apoptosis." (PMID 40361560, 2025). "Several key pathways are implicated in SCLC progression and tumor-endothelial interactions, most notably notch receptor (NOTCH), mechanistic target of rapamycin kinase (mTOR) and mitogen-activated protein kinase (MAPK) signaling pathways." (PMID 41551597, 2025). "Clinical observations further indicate that it suppresses key tumor-promoting pathways such as mTOR and STAT3." (PMID 41010968, 2025). "These drugs largely target critical cellular processes such as DNA replication and the PI3K/MTOR signaling pathway, both of which are essential for tumor progression." (PMID 41019288, 2025). "This quantitative mapping highlights tumor lineages with concentrated mTOR-axis dependency, guiding biomarker-driven and lineage-specific studies." (PMID 41300706, 2025). "In contrast, adi‐CAFs and infla‐CAFs showed upregulation of pathways associated with tumor progression, including Hedgehog, PI3K/Akt/mTOR, Wnt/β‐Catenin, and TGF‐β signaling pathways." (PMID 40433916, 2025). "The RAS/RAF/MEK/ERK and PI3K/AKT/mTOR cascades represent key signaling routes whose dysregulation contributes to tumor growth, survival, and therapeutic resistance in tumors harboring alterations such as KRAS, BRAF, PIK3CA, or PTEN." (PMID 41465387, 2025). "Many studies have shown that the mTOR signaling pathway plays an important role in regulating tumor metabolism, tumor cell proliferation and metastasis." (PMID 39895786, 2025). "Specifically, PLOD2 regulates the PI3K/Akt/mTOR signaling pathway, which enhances glycolysis and tumor progression." (PMID 41220952, 2025).
tumor (continued). "They found that ITGB8/TRIM59/AKT/mTOR/glycolysis pathways were upregulated in bladder cancers with soft tumor cells." (PMID 40723250, 2025). "Emerging evidence suggests mTOR inhibitors amplify tumor vaccine efficacy through both systemic delivery and ex vivo DCs treatment." (PMID 40924040, 2025). "PI3K/AKT/mTOR inhibitors (e.g., everolimus, paxalisib) suppress tumor growth, while epigenetic modulators (EZH2, BET inhibitors) enhance immune recognition." (PMID 40223940, 2025). "In contrast, in poorly vascularized tumor areas, mTOR and eIF4E are inactive, while 4EBP1 is activated, which thus facilitates tumor cell survival and favors tumor growth in the long term." (PMID 40670359, 2025). "In these high-grade tumors, PTEN loss contributes to rapid tumor growth, early metastasis, and therapeutic resistance, particularly in therapies targeting the PI3K/AKT/mTOR pathway." (PMID 40072110, 2025). "The PI3K/AKT/mTOR pathway, often altered through PIK3CA mutations or PTEN loss, regulates tumor growth and contributes to resistance against upstream inhibitors." (PMID 41228293, 2025). "As discussed later, combination therapies targeting both mTOR and MEK pathways are now being investigated for some NF1-associated tumor types." (PMID 41294711, 2025). "The compound has been observed to induce apoptosis, hinder tumor growth, and diminish oxidative stress by regulating primary molecular pathways, which include mTOR/AKT/PI3K, NF‐kB, and Wnt signaling." (PMID 40661795, 2025). "This suggests that Urolithin A mediates protective autophagy and cell apoptosis through the PI3K/AKT/mTOR pathway induction, ultimately inhibiting tumor progression and reducing chemotherapy drug toxicity." (PMID 40066330, 2025). "The mTOR pathway was found to inhibit ferroptosis in tumor cells through the activation of SREBP1/SCD1." (PMID 40140647, 2025). "Inhibiting BCAA metabolism can reduce tumor cells’ access to BCAAs, decreasing mTOR pathway activity, thereby inhibiting tumor growth and metastasis." (PMID 40438606, 2025). "Lipids such as cholesterol and phospholipids not only serve as structural elements of cellular membranes but also act as signaling molecule carriers, regulating critical pathways like PI3K/AKT/mTOR to influence tumor cell proliferation and survival." (PMID 41030951, 2025). "The two tumor suppressor genes that are commonly mutated are TSC1 and TSC2, which leads to the hyperactivation of the MTOR pathway." (PMID 40564038, 2025). "To confirm the involvement of the PI3K/AKT/mTOR pathway in the tumor-suppressive effects of β-lapachone, we conducted rescue experiments using the PI3K pathway activator 740Y-P." (PMID 40051559, 2025). "One of the downstream effectors of RAC1, mammalian target of rapamycin (mTOR), promotes tumor cell metabolism including glycolysis and lipid biosynthesis." (PMID 41160695, 2025). "The PI3K/PKB pathway, also known as the Akt/mTOR pathway, is a complex intracellular pathway that drives cell growth and tumour proliferation." (PMID 41160271, 2025). "The significant association between PI3K pathway alterations and poorer survival in NHW patients supports previous studies demonstrating that PI3K/AKT/mTOR signaling is a critical driver of tumor progression and therapy resistance in GC." (PMID 40227587, 2025). "mTOR inhibitors, including rapamycin and its analogs (temsirolimus and everolimus), have been studied for their ability to inhibit autophagy-mediated tumor growth." (PMID 40710325, 2025). "Given the overactive PI3K/AKT/mTOR axis in GBM, the preclinical study for the dual inhibition of AKT with perifisone and mTOR with temsirolimus, has already shown synergistic anti‐tumor effects." (PMID 38105543, 2025). "This can be explained due to the combined effects of LAM cell involvement, enhanced mammalian target of rapamycin (mTOR) signaling, hormonal sensitivity, and possibly more aggressive tumor biology." (PMID 40755676, 2025).
tumor (continued). "PTEN has its tumour suppressor function frequently suppressed; this gene is a negative P13K/AKT pathway regulator, frequently associated with mTOR inhibitor sensitivity." (PMID 41573648, 2025). "In KRAS-mutant colorectal cancer, inhibition of the AKT/mTOR signaling pathway enhances tumor cells sensitivity to ferroptosis and significantly inhibit tumor progression." (PMID 41479924, 2025). "Podophyllotoxin down-regulates the phosphorylation level of Akt or mTOR to inhibit tumor cell proliferation; meanwhile, it up-regulates PTEN to inhibit Akt activation." (PMID 41050074, 2025). "In melanoma, the binding of PD-1 onto tumor cells with PD-L1 expressed by the surrounding tumor or stromal cells can activate the mTOR signaling pathway, thereby directly promoting tumor growth independently of immune cell interactions." (PMID 40508177, 2025). "Among these, shikonin has been reported in various tumor models to exert antitumor effects by modulating the mTOR pathway." (PMID 40949144, 2025). "Previous studies have demonstrated that citrate suppresses tumor growth by inhibiting calcium signaling, mTOR and glycolysis pathways." (PMID 40165944, 2025). "This IR-driven pathway activates oncogenic signaling, specifically the PI3K/Akt/mTOR pathway, thereby facilitating tumor progression and contributing to resistance against therapeutic interventions." (PMID 41210510, 2025). "The modulation of autophagy via pathways such as mTOR and AMPK, alongside emerging regulators like non-coding RNAs, underscores its critical function in mitigating skin damage caused by UV radiation." (PMID 40421222, 2025). "The constant activation of mTOR leads to uncontrolled growth and metabolic reprogramming characterized by enhanced glycolysis and amino acid uptake, which not only fuels tumor cell anabolism but also shapes the immune microenvironment." (PMID 40673277, 2025). "Knockdown of circ_0092278 reduced PTC cell proliferation, migration, invasion, and tumor growth by inhibiting the PI3K/Akt/mTOR pathway." (PMID 40537911, 2025). "Research has demonstrated that pathways such as Wnt, MAPK, and Phosphatidylinositol-3-kinase (PI3K)/AKT/mammalian target of rapamycin (mTOR) can promote tumor development and progression." (PMID 40489463, 2025). "mTOR inhibitors, including sirolimus and everolimus, have demonstrated anti-tumor effects both in vitro and in vivo, with newer agents targeting mTORC1 and mTORC2 showing improved efficacy." (PMID 41300430, 2025). "Targeted therapies, including inhibitors for pathways like EGFR and PI3K/mTOR, have shown some promise, though challenges persist due to tumor heterogeneity and resistance mechanisms." (PMID 39796773, 2025). "At the mechanistic level, tumor cell-intrinsic epileptogenesis involves mTOR-driven proliferation and alterations in cell morphology, including somatic hypertrophy and ectopic axon growth." (PMID 41074169, 2025). "Multiple clinical trials have shown that metformin administration during the EC surgical window reduces Ki67 expression in tumor tissue while altering the phosphorylation status of PI3K/AKT/mTOR pathway proteins." (PMID 40391161, 2025). "Angiogenesis, invasion, metastasis, and tumor formation are all primarily influenced by mTOR, a downstream molecule of the PI3K/AKT signal pathway." (PMID 41374963, 2025). "The AKT/mTOR signaling pathway is a key regulator of cellular processes, including apoptosis inhibition, tumor progression, and chemoresistance." (PMID 40565099, 2025). "The mTOR pathway is frequently hyperactivated in GBM and is strongly linked to enhanced tumor cell survival, metabolic adaptation, and aggressive growth." (PMID 41154521, 2025). "For example, insulin can directly activate the PI3K/AKT/MTOR/S6K signaling pathway in tumors, and promote the increase of NF-KB to regulate cell proliferation and tumor metastasis." (PMID 40756516, 2025).
tumor (continued). "Currently, the most established strategy for targeting the mTOR pathway involve directly inhibiting the tumor's mTOR pathway to reduce its metabolic rate, thereby alleviating the burden on NK cells for substance and energy uptake in the TME." (PMID 40959206, 2025). "This feature is beneficial for modulating autophagy by allowing targeted intervention in the PI3K/AKT/mTOR pathway within the tumor microenvironment." (PMID 40076496, 2025). "Alterations in the mTOR pathway have been well documented in RCC and are implicated in tumor progression and metastasis." (PMID 41465847, 2025). "The PI3K/AKT/mTOR signaling pathway is a well-established regulator of numerous biological processes, including cell proliferation, differentiation, invasion, and tumor growth." (PMID 39873475, 2025). "Mammalian target of rapamycin (mTOR) is a promising target due to its central role in regulating tumour growth, proliferation and metastasis." (PMID 40461777, 2025). "Consistent with prior research, which links mTOR pathway inhibition to reduced tumor proliferation, invasion and migration, our findings underscore the therapeutic potential of targeting this pathway in LUAD." (PMID 39962118, 2025). "Neoadjuvant therapy with mTOR inhibitors has shown promise in improving surgical outcomes by reducing tumor size, enhancing the tumor–brain interface, and decreasing vascularization." (PMID 40141713, 2025). "In contrast, M2 polarization, associated with tumor promotion, is activated by signals like IL-4, IL-10, and TGF-β, primarily through the JAK/STAT6, PI3K/AKT/mTOR, and TGF-β/SMAD pathways, promoting tissue repair, immune suppression, and angiogenesis." (PMID 40330466, 2025). "This oxidative shift subsequently suppresses the PI3K/AKT/mTOR signaling axis, promoting autophagy in tumor cells." (PMID 40959527, 2025). "Enhanced interactions between immune cells and fibroblasts further highlight their role in promoting tumor development through signaling pathways such as Notch and mTOR." (PMID 39936948, 2025). "Combining NCAPH-KD with an mTOR inhibitor (Everolimus, Eve) or a cyclin-dependent kinase inhibitor (Flavopiridol, Flav) shows a promising anti-tumor effect in PCa cells both in vitro and in vivo." (PMID 39991770, 2025). "It is imperative for subsequent research to delineate more precisely the roles of the mTOR pathway in both tumor and immune cells within the context of HNSCC." (PMID 40444100, 2025). "Sirolimus, an mTOR inhibitor, is an immunosuppressant with activities that can restrain tumor growth, including anti-proliferative, anti-angiogenic and pro-immunogenic effects." (PMID 40061426, 2025). "LncRNA LINC00511 has been implicated in cisplatin resistance through its role in activating the PI3K/AKT/mTOR pathway, which supports tumor survival and proliferation." (PMID 41480385, 2025). "Smurf1 plays a bidirectional regulation of the mTOR‐TFEB axis in the balance between tumor growth and stress‐induced cell homostasis." (PMID 40958774, 2025). "To validate the RNA analysis, we quantified with IF the level of mTOR protein, confirming the presence of the protein exclusively within the actual tumor tissue and the B16F10–NIH/3T3 spheroids." (PMID 41220928, 2025). "Our findings reveal that patients in cluster 1, characterized by higher TMB, more active proliferative signaling (PI3K/AKT/mTOR), and elevated Ki-67 expression, exhibited more aggressive tumor features and relatively poorer clinical outcomes." (PMID 40612672, 2025). "Within cancerous cells, metabolic reprogramming of AAs is intrinsically linked to the synthesis of proteins and nucleotides, modulation of signalling pathways such as mTOR, regulation of tumour metabolism, and epigenetic modifications." (PMID 41400898, 2025).
tumor (continued). "TSC is caused by heterozygous pathogenic variants in either the TSC complex subunit 1 (TSC1) or the TSC complex subunit 2 (TSC2) tumor suppressor genes, which lead to overactivation of the rapamycin (mTOR) pathway and tumor formation in multiple organs." (PMID 40861726, 2025). "PTEN functions as a tumor suppressor by modulating the PI3K/AKT/mTOR pathway, ultimately influencing different biological responses, including cell growth." (PMID 41009024, 2025). "By suppressing the synthesis of pro-inflammatory cytokines and growth factors, CR-mediated mTOR inhibition creates a less favorable microenvironment for tumor initiation and invasion." (PMID 39940361, 2025). "Overall, the enriched pathways—mTOR signaling, lysosomal function, protein transport, and autophagy regulation underscore key mechanisms of tumor survival and therapeutic resistance." (PMID 41168571, 2025). "The mTOR inhibitors like everolimus can reverse this immune escape, increase the infiltration and cytotoxic function of anti-tumor immune cells, and synergize with ICIs." (PMID 41472727, 2025). "Targeting this metabolic vulnerability with the potent and selective ASCT2 inhibitor V9302 effectively suppressed AKT/mTOR signaling, induced apoptosis, and inhibited tumor growth in preclinical models of SS." (PMID 41514527, 2025). "The dependency of tumor cells on glutamine availability, provided either by neighbor cells or through the blood stream can be modulated by mTOR activity." (PMID 38105543, 2025). "Frequent activation of the PI3K/mTOR pathway contributes to tumor growth and immune invasion; inhibition of this pathway has shown to transform the TME and sensitize uLMS to PD-1 blockade in preclinical models." (PMID 41303434, 2025). "High BCAT1 levels are associated with tumor proliferation and invasion, partly through activation of PI3K/Akt/mTOR and Wnt/β-catenin signaling cascades." (PMID 41502503, 2025). "In summary, the PI3K/AKT/mTOR pathway represents a critical target for understanding tumor radioresistance and developing novel therapeutic strategies." (PMID 40725100, 2025). "The change in the activity of the mTOR complex drives cell proliferation, inhibits apoptosis, and promotes metabolic reprogramming to fulfill the requirements of rapid tumor cell growth." (PMID 40149733, 2025). "↓ PI3K/AKT/mTOR signaling → ↓ tumor cell survival → ↑ temozolomide (TMZ) sensitivity and reduced chemoresistance." (PMID 40761486, 2025). "In esophageal cancer, FABP4 inhibits AMPK phosphorylation, activates mTOR signaling, and promotes tumor cell proliferation." (PMID 40717587, 2025). "Immune cells activate key signaling pathways, such as PI3K/Akt, MAPK, and mTOR, through T-cell receptors (TCRs), which directly impact immune response and tumor clearance." (PMID 41347091, 2025). "The interplay between GI-lncRNAs and pivotal oncogenic pathways like PI3K/AKT/mTOR further highlights their potential as mediators of tumor progression." (PMID 40149330, 2025). "Everolimus directly targets the phosphoinositide 3-kinase (PI3K)/AKT/mTOR pathway to suppress tumor growth and proliferation." (PMID 41050082, 2025). "For example, it inhibits the PI3K/Akt/mTOR pathway, often upregulated in chemoresistant tumor cells, thereby enhancing the apoptotic response." (PMID 40806510, 2025). "Growth factor signaling, such as the RTK/PI3K/AKT/mTOR pathway, further amplifies glucose metabolism in tumor cells." (PMID 41281744, 2025). "High expression of Ang-1 in CM promotes tumour cell proliferation, migration, and epithelial-mesenchymal transition by activating the Akt/mTOR signalling pathway, thereby driving tumour progression." (PMID 41160271, 2025). "One key route involves activation of bypass pathways such as PI3K/AKT/mTOR, allowing tumor cells to maintain growth despite BRAF inhibition." (PMID 41008893, 2025).